RB1 (RB transcriptional corepressor 1)
Diseases named in the same sentence as RB1 in open-access papers (continued):
Sharing a sentence is not in itself a finding about the gene and the disease.
neuroendocrine tumors (34 papers, 2012 to 2026). "Inactivating mutations or homozygous deletions in RB1 have been reported in neuroendocrine neoplasms of the lung, gastrointestinal tract, and prostate." (PMID 33737597, 2021). "RB1 was expressed in 44.5% of neuroendocrine tumor tissue, and 5 (55.5%) patients showed a loss of expression." (PMID 30627226, 2018). "Another type of neuroendocrine tumor, small cell lung tumors, nearly always contains RB1 mutations." (PMID 32198354, 2020). "Taken together, the precise distinction of high-grade neuroendocrine tumors representing as type I LCNECs and as RB1-mutated SCLC or type II LCNECs, may be pivotal to assess the efficacy of targeted therapeutics, including Notch pathway and immune checkpoint inhibitors." (PMID 29535388, 2018). "Heterozygous deletion of Rb1 (Osx1‐Cre;Rb1+/lox;p53lox/lox) lengthens latency but reduces the incidence of neuroendocrine tumors." (PMID 41170752, 2025). "For example, recent reports have shown that N-Myc/AKT overexpression and Rb1/PTEN knockdown can induce neuroendocrine tumors in transgenic mice and xenografts." (PMID 29156689, 2017). "At necropsy, Rb1+/− mice were evaluated for the presence of neuroendocrine tumors and lung metastases." (PMID 23454836, 2013).
pancreatic cancer (34 papers, 2012 to 2025). "Public genomic databases of pancreatic cancer revealed that RNASEH2B is commonly co-deleted with retinoblastoma 1 (RB1) and BRCA2, three closely located genes on chromosome 13q." (PMID 39968096, 2025). "Significantly, median sensitivity in the RB1-defective group was comparable to that of the pancreatic cancer line CAPAN1, known for profound PARPi sensitivity due to defective BRCA225 that we included to benchmark clinically relevant response levels." (PMID 34862364, 2021). "Hypermethylation of RB1 promoter was previously found in human cancers, and down-regulation of RB1 was reported in pancreatic cancer." (PMID 34516908, 2021). "Genomic analyses indicated that a similar phenotype exists in pancreatic cancer in which CDK4 regulates RB1 activation." (PMID 33282875, 2020). "A recent publication describes an overrepresentation of hsa-miR-132-3p and hsa-miR-212 in pancreatic cancer and shows that RB1 is a target of these miRNAs by a luciferase UTR assay." (PMID 23560086, 2013). "MiR-221-3p by targeting RB1 could increase proliferation, migration, and invasion and also confer resistance for 5-FU in pancreatic cancer cells via the EMT signaling pathway." (PMID 33954114, 2021). "In pancreatic cancer cell lines miRNA-221-3p overexpression correlates with reduced sensitivity to 5-fluorouracil and gemcitabine and increased migration, possibly via inhibition of RB1." (PMID 31979312, 2020). "Found a 7 gene panel (MDR1, SRBC, VHL, MUC2, RB1, SYK, and GPC3) that detects colorectal and pancreatic cancers with 63.16% sensitivity, 84% specificity, and AUC of 0.8177." (PMID 36980276, 2023). "Drugs targeting the cyclin-dependent kinase 4/6 (CDK4/6)–retinoblastoma 1 (RB1) axis have shown efficacy against multiple solid cancers, but their therapeutic potential in pancreatic cancer remains poorly defined." (PMID 33282875, 2020). "Similarly, the higher expression of the RB1 and CDK6 genes was correlated with poor overall survival in pancreatic cancer patients." (PMID 39123441, 2024). "In 5-FU resistant pancreatic cancer cells, the overexpression of miR-221-3p promoted the cell proliferation, migration, invasion, and epithelial-mesenchymal transition (EMT) by inhibiting RB1 expression." (PMID 31222560, 2019).
astrocytoma (32 papers, 2002 to 2024). "A mutation of the 13q14 gene encoding RB1 exists in approximately 30% of all higher-grade astrocytomas." (PMID 34687436, 2022). "In astrocytomas, loss of heterozygosity in RB1 is the most common event and is associated with increased tumor cell proliferation and decreased survival in more than one third of patients." (PMID 26317630, 2015). "RB1 can also carry point mutations which are often heterozygous and have been suggested to play a less clear role in disease aggressiveness, whereas homozygous RB1 deletions have been linked to high-grade IDHmut astrocytomas and disease aggressiveness." (PMID 37932833, 2023). "In PMMRDIA, the RB1 gene was affected by point mutations more frequently (23.5% vs. 4.6%) whereas deletions of CDKN2A/B were present less frequently (35% vs. 70%) compared to the reference cohort of high-grade supratentorial IDH-mutant astrocytomas." (PMID 33216206, 2021). "In order to study readthrough induction of nonsense mutant RB1 by G418, we used human SW1783 astrocytoma cells that carry endogenous R579X nonsense mutant RB1 with a UGA PTC." (PMID 37917619, 2023). "Meanwhile, other molecular biomarkers indicating worse outcome in IDH‐mutant astrocytoma, including NOTCH1 mutations and incomplete resections in oligocytoma and PIK3R1 mutations, RB1 mutations and CDK4 mutations and amplifications in astrocytoma." (PMID 37667984, 2023). "In grade II astrocytomas, a moderate inverse correlation was observed only between the expression of RB1 and Bmi-1 (r = -0.5968, p = 0.001)." (PMID 26317630, 2015). "RB1 was homozygously deleted in three grade 2–3 IDHmut astrocytomas with poor OS rates." (PMID 37932833, 2023). "Therefore, the inhibition of the components of RB1 pathway might be a promising strategy for the treatment of various malignant cancer types, including astrocytoma, adenocarcinoma, basal cell carcinoma, and gastrointestinal tract endocrine tumor 60-64." (PMID 36483593, 2022). "Moreover, we further detected the effect of miR-335 on Rb1 expression in astrocytoma cells." (PMID 21592405, 2011). "Both within GLASS and TCGA IDHmut astrocytomas, the inactivation of CDKN2A and RB1 was mainly mutually exclusive." (PMID 37932833, 2023). "As expected, recurrent homozygous deletions in CDKN2A and RB1 were present in TCGA diffuse gliomas and GLASS progressed grade 4 IDHmut astrocytomas." (PMID 37932833, 2023).
astrocytoma (continued). "In our cohort of IDH-mutant diffuse glioma, EGFR Amp was found to co-occur with FGFR1, FGFR2, NTRK3 and RB1 alterations, which was not completely consistent in astrocytoma and oligodendroglioma." (PMID 38595969, 2024). "Although hypermethylation of the RB1 promoter region is the second most common event in astrocytomas, our results indicate that RB1 was not methylated in all the samples analyzed, regardless of the tumor grade." (PMID 26317630, 2015). "A recent report has found an increase of promoter hypermethylation in CALCA and CDH1 genes in high-grade astrocytomas, but they did not see any remarkable methylation frequency of other classical tumor suppressor genes, such as p14ARF, RB1, CDKN2B, or APC." (PMID 22389839, 2012). "Seventeen genes (ABL, APC, APAF1, BRCA1, CSPG2, DAPK1, hMLH1, LKB1, PTEN, p14ARF, p15INK4b, p27KIP1, p57KIP2, RASSF1C, RB1, SURVIVIN, and VHL) displayed a uniformly unmethylated pattern in all the astrocytoma and non-astrocytoma tissues examined." (PMID 15367334, 2004).
neuroblastoma (30 papers, 2014 to 2025). Neuroblastoma (NB) is the most common solid, extracranial childhood tumor. "While Rb1 loss is very rare in neuroblastoma, several studies have shown that the cyclin D/CDK4/CDK6 pathway is hyperactive in neuroblastoma." (PMID 34893606, 2021). "Overexpression of CDK4/6 or Rb1 knockout confers neuroblastoma cell resistance to both palbociclib and the KDM6 inhibitor GSK-J4." (PMID 34893606, 2021). "This indicated that the AKT signaling pathway was involved in the transportation of FOXO1 and RB1 by XPO1.Our research confirmed that verdinexor inhibited neuroblastoma proliferation and induced apoptosis through nuclear accumulation of FOXO1 and RB1." (PMID 34384466, 2021). "E2F family deregulation especially occurs in recurrent neuroblastomas and tumor-derived cell lines, presumably caused by upregulation of factors, such as CDK4, that inhibit the RB1 tumor suppressor." (PMID 28036269, 2017). "Based on that, we speculated that in the context of amplified MYCN, a positive RB1 expression might positively sensitize neuroblastoma cells to CDK4/6 inhibitors." (PMID 36982482, 2023). "We conclude that GSK461364 treatment not only induces expression patterns associated with a G2/M arrest, but might also inhibit G1/S transition via the RB1-E2F axis in neuroblastoma cells." (PMID 28036269, 2017). "Verdinexor, the specific inhibitor of XPO1, suppressed the neuroblastoma cell growth and induced cell apoptosis by FOXO1 and RB1 nuclear accumulation through inhibition of the PI3K/AKT pathway." (PMID 34384466, 2021). "Re-analysis of an independent RNA-seq data set43 also showed that KDM6 inhibition led to downregulation of gene sets enriched with Rb1 knockout and DREAM complex (dimerization partner, RB-like, E2F, and multi-vulval class B) in neuroblastoma cells." (PMID 34893606, 2021). "Inhibition of XPO1 by the specific inhibitor verdinexor suppressed neuroblastoma cell growth and induced cell apoptosis through FOXO1 and RB1 nuclear accumulation by inhibiting the PI3K/AKT pathway." (PMID 34384466, 2021).
colon carcinoma (29 papers, 2006 to 2025). "In our present study, MDM2 downregulation in HT-29 colon cancer cells was associated with RB1 upregulation upon 5-ISA-fortified lettuce extracts as compared to control lettuce." (PMID 36296971, 2022). "Interestingly, RBBP4, a downstream regulator of RB1, is upregulated by RB1 mutation and enhances mesenchymal marker expression in human cervical and colon cancer cell lines." (PMID 36230849, 2022). "Rbfox2 levels were elevated in colon cancer tissue relative to normal colon tissue, whereas RB1 protein levels were lower in cancer tissue." (PMID 31028247, 2019). "Most colon cancer tissues displayed low RB1 protein levels relative to normal colon tissues, whereas Rbfox2 levels in colon cancer tissue were significantly higher than those in normal colon tissue." (PMID 31028247, 2019). "Most notably, the well-known tumor suppressor RB1 shows strong oncogene-like signal in colon cancer." (PMID 27321817, 2016). "While Rb1 is inactivated in the majority of the malignancies, some types of cancers, such as colon cancer, require constitutive RB1 expression to maintain proliferation and prevent apoptosis." (PMID 25755634, 2015). "The top oncogenic signatures identified from male smoking include tumor suppressor genes (PTEN and RB1), colon cancer gene sets (CTIP and SNF5), skin tumor progression protein (ATF2), oncogenic signatures KRAS-600-LUNG and E2F3 pathway genes." (PMID 25621181, 2014). "MDM2 downregulation in HT-29 colon cancer cells was associated with RB1 upregulation upon 5-ISA-fortified lettuce extracts, which provides a link to the epigenetic regulation of tumor suppressor genes by RB/MDM2 pathway." (PMID 36296971, 2022). "Additionally, we observed that Rbfox2 localized to the cytoplasm of human colon cancer cells and that RB1 protein levels were very low in human colon cancer tissue." (PMID 31028247, 2019). "Additionally, we observed significantly lower RB1 protein levels in human colon cancer tissues than in normal tissues and found that Rbfox2 plays an important role in cell cycle progression, regardless of cellular stress." (PMID 31028247, 2019). "Support for the hypothesis of a proapoptotic role of RB1 in some circumstances also comes from a study reporting that RB1 knockdown reduced the toxicity of histone deacetylase (HDAC) inhibitors in colon cancer cells." (PMID 26160835, 2015). "miR-192 also benefits the prognosis of colon cancer patients by regulating SRPX2, Rab-2A, RhoA-ROCK-LIMK2, farnesoid X receptor, RB1/E2F1 pathway, and NOD2." (PMID 33614788, 2021).